FOXP3 (forkhead box P3)
Diseases named in the same sentence as FOXP3 in open-access papers (continued):
Sharing a sentence is not in itself a finding about the gene and the disease.
asthma (continued). "Tregs also play an essential role in allergic responses in asthma and FOXP3 is the master regulator of Tregs." (PMID 27777592, 2016). "The regulation of FOXP3 expression by methylation at its proximal promoter and an intronic regulatory element is well-established and studies from twins discordant for asthma indicate that this mechanism is important for asthma development." (PMID 27777592, 2016). "Our study also identified, for the first time, reduced numbers of CD3+CD4+FOXP3+ Treg cells in patients with severe asthma." (PMID 25746968, 2015). "In this line, differential methylation of FOXP3 and IFNγ promoter regions was demonstrated in isolated peripheral regulatory and effector T cells from 21 monozygotic twin pairs discordant for asthma (age range 9 to 76 years)." (PMID 26052354, 2015). "Several lines of evidence point to the involvement of epigenetic changes in the FOXP3 locus of Treg cells in asthma phenotypes." (PMID 27965764, 2015). "Several lines of evidence show that epigenetic changes in the FOXP3 locus of Treg cells influence the asthma phenotypes." (PMID 27965764, 2015). "Our data showed that GATA3, miR-125a-5p, FOXP3 and IL-6R are perturbed in the Treg cells of asthma patients." (PMID 26424054, 2015). "Studies have shown that expression of the FOXP3 gene is reduced in patients with asthma and allergies compared to healthy controls." (PMID 27965764, 2015). "This review discusses some aspects of the role of FOXP3 in the development of asthma and allergy, with a particular emphasis on genetic and epigenetic factors." (PMID 27965764, 2015). "One study linked differential DNA methylation in the vicinity of two candidate genes (FOXP3 and IFNγ) with asthma in a study of N = 21 asthma-discordant adult monozygotic (MZ) twin pairs." (PMID 26691723, 2015). "Systemic vitamin D status correlated directly with airway levels of IL-10 and CD4+FoxP3+ T cells in pediatric asthma patients and in healthy controls." (PMID 25852682, 2015). "Both proportion and cell counts of CD4+IL-17A+ cells increased and CD4+Foxp3+ cells decreased in asthma model." (PMID 26612993, 2015). "The present review aims to provide an overview of FOXP3 role in immune regulatory processes as well as a discussion of the implications of this activity on allergic diseases, specifically asthma and allergic rhinitis." (PMID 27965764, 2015). "A significantly higher percentage of CD4+Foxp3+ cells from asthma patients expressed IFN-γ (P = 0.01), IL-4 (P = 0.004) and CD25 (P = 0.04), whereas the percentage of CD4+IL-10+ cells expressing Foxp3 was significantly decreased in asthmatics (P = 0.03)." (PMID 25132806, 2014). "Recent work has demonstrated that Foxp3 expression is reduced and CD25(hi) Treg-suppressive function is deficient in asthma." (PMID 24886492, 2014). "Dysregulated T helper type 2 (Th2)-biased immune responses directed against antigens and impaired CD4+CD25+ forkhead box P3 (FoxP3)+ Treg cells play important roles in the development of asthma." (PMID 25177863, 2014). "Our study is the first to show the decreased population of CD4+Foxp3+TGF-β+ cells in BAL fluid of asthma patients." (PMID 25132806, 2014). "In severe asthma, sensitized and challenged mice showed 16 and 17-times higher Tbet and Foxp3 expression, respectively, when compared to control, sensitized only and challenged only mice." (PMID 23781124, 2013). "Previous studies have shown that CD4+CD25+ Foxp3+ Treg cells inhibit the development and progression of allergic diseases including asthma." (PMID 23617952, 2013). "In mild asthma, the largest change (9-fold) was observed in Foxp3 expression followed by Tbet, Gata3, and Rorγt." (PMID 23781124, 2013). "We tested the expression of IL-17A, RORγ(t) and FOXP3 in peripheral blood T-lymphocytes from intermittent and mild-moderate asthma." (PMID 23573194, 2013).
asthma (continued). "Our results are in accordance with other authors that have reported changes in frequency of CD4+CD25+ T cells and CD4+CD25+FOXP3+ regulatory T cells in atopic diseases, such as asthma, rhinitis, and atopic dermatitis." (PMID 24368924, 2013). "In cultured T-lymphocytes IL-17A and RORγ(t) expression were higher in mild-moderate asthma/persistent rhinitis than in mild-moderate asthma/intermittent rhinitis, while FOXP3 was reduced." (PMID 23573194, 2013). "In severe asthma, Foxp3 and Tbet showed the highest expression in lungs of allergen-sensitized and challenged mice." (PMID 23781124, 2013). "The number of Foxp3+ cells tended to increase and their activity, measured by IL-10 production, increased after sitostanol treatment in PBMCs from asthma patients compared to controls by 32.3% (p = 0.077) and 13.3% (p<0.05), respectively." (PMID 23091602, 2012). "Our investigation demonstrates that an increase in methylation of CpG sites within FOXP3 and IFNγ results in decreased protein expression and is associated with impaired T cell function that vary by SHS exposure and asthma diagnosis among MZT." (PMID 23226205, 2012). "The levels of Foxp3 mRNA in BAL from children with asthma are lower than in healthy controls, positively correlate with FEV1 and, after 4 weeks of treatment with inhaled corticosteroids, significantly increase." (PMID 23251336, 2012). "Recently, studies from our lab demonstrated a role for epigenetics in regulating asthma as increased CpG methylation of FOXP3 reduced lung function and increased asthma diagnosis." (PMID 23226205, 2012). "Oral administration of bacterial products has been shown to prevent asthma via recruitment of Foxp3+ Tregs." (PMID 23071726, 2012). "DNA methylation of the Foxp3, ACSL3, and ARG2 loci are associated with impaired regulatory T-cell function, increased asthma morbidity, and exhaled nitric oxide production, respectively." (PMID 22740325, 2012). "Another study found that circulating FOXP3+/CD4+ ratio was significantly low in patients with asthma and atopic dermatitis." (PMID 22164170, 2011). "In humans affected by asthma, FOXP3 protein expression within CD4+CD25high T-cells is significantly decreased compared to controls." (PMID 21843342, 2011). "An important role for CD4+CD25+FoxP3+Tregs to immune regulation of a variety of chronic inflammatory disease scenarios including asthma has been noted." (PMID 19769993, 2010). "In addition, PD-1 and PD-L1 expression was found to be increased, and FOXP3 expression decreased in the small intestine and lungs, which further exacerbated airway inflammation in asthma." (PMID 40401951, 2025). "Additionally, the downregulation of IFNG and FOXP3 in asthma patients indicates suppression of regulatory immune responses." (PMID 40309741, 2025). "Similarly, probiotics administered to asthma patients increased FOXP3 and Treg levels while suppressing the Th17-mediated inflammatory response, leading to improved asthma symptoms." (PMID 39465678, 2025). "In childhood asthma, specific epigenetic alterations, such as acetylation of the Foxp3 and IL13 genes, have been shown to influence immune regulation, further linking early-life epigenetic modifications to an increased susceptibility to asthma." (PMID 40806756, 2025). "In addition, disruption of Th17/Treg balance caused by activation of STAT3/RORγt-STAT5/Foxp3 signaling pathway aggravated WSI-TRPM2.5 and Oe-TRPM2.5-induced asthma exacerbation further supported our conclusion." (PMID 39444792, 2024). "Various studies have looked at altering FOXP3 levels in asthma." (PMID 36981683, 2023). "Foxp3+ Treg cells regulate Th2 responses and inhibit allergy and asthma." (PMID 36430662, 2022). "Likewise, the Imuno TF also influenced gene expression of T-bet and Foxp3 once asthma mice treated with Imuno TF presented restoration, even if partially, of gene expression for T-bet (7A) and Foxp3 (7B) compared to asthma group." (PMID 36685604, 2022).
asthma (continued). "However, several reports have demonstrated increases in the number of Tregs during exacerbation of asthma and elevated Treg numbers and FOXP3 expression after allergen challenge or glucocorticoid treatment." (PMID 34072455, 2021). "Therefore, CD4+CD25+Foxp3+ TReg cells are considered as one kind of target cells for allergen-specific immunotherapy in asthma." (PMID 34630778, 2021). "In addition, Foxp3+ Treg cells can attenuate Th2- and Th17-cell-mediated airway inflammation and hyperresponsiveness both in animal models and in patients with asthma." (PMID 33806085, 2021). "In addition, down-regulation of miRNA-221-5p induced the protein expression of suppressor of cytokine signaling 1 (SOCS1) and receptor-related orphan receptor-gamma-t (RORγt) and suppressed that of FOXP3 in in vitro model of asthma." (PMID 34863307, 2021). "Ambient air pollution (AAP) could impair Treg cell function and aggravate the symptoms of asthma via the upregulation of Foxp3 methylation levels." (PMID 34239942, 2021). "In patients with Henoch-Schönlein purpura (HSP) or asthma, methylation-based silencing of the related genes (e.g., Foxp3, suppressor of cytokine signaling 1 (SOCS1), and SOCS3) disturbed the Treg/Th17 cell balance and critically contributed to pathogenesis of related diseases." (PMID 34239942, 2021). "Additionally, FOXP3+Tregs were induced after glucocorticoid treatment in asthmatic patients, suggesting a crucial role of FOXP3+ Treg cells in asthma development and therapy." (PMID 34691038, 2021). "The increase of Treg (CD4+CD25+FOXP3+) after PMBL® treatment may be the possible mechanism that prevents asthma exacerbations and reduces the severity of this disease." (PMID 33472687, 2021). "The role of Tregs in asthma is scanty, and quite a few studies have reported their clinical benefits, which show that depletion of FOXP3+ Tregs augments, whereas the reconstitution of Tregs subdues lung allergic responses and in some studies of airway hyperresponsiveness (AHR)." (PMID 33267824, 2020). "Foxp3 binds upstream of the fetal lungnitrate reductase catalytic subunit (NAPA) gene located on chromosome 1p36 to inhibit atrial natriuretic peptide (ANP) production, a molecule associated with asthma." (PMID 33339172, 2020). "Although miR-15a has not been directly associated with asthma pathogenesis, a mouse model of graft versus host disease found that the over-expression of miR-15a in cord blood leads to the inhibition of the FOXP3 gene." (PMID 33291534, 2020). "Data collected from patients with asthma further highlighted the crucial role of Treg, which reported lower Tregs ratio and FOXP3 mRNA expression, and lower levels in peripheral blood mononuclear cells may be associated with asthma pathogenesis in humans." (PMID 33267824, 2020). "Promotion of Foxp3 expression, which is consistent with previous reports that other DNA methylation inhibitors also activate Foxp3 expression in murine models of asthma, EAE and diabetes, explained the significant alleviation of intraocular inflammation found in EAU mice." (PMID 31475011, 2019). "Our study revealed the importance of sialyl LeX positive FOXP3+CD25+ Treg cells in asthma." (PMID 31222115, 2019). "Older humans suffering from asthma also display a lower FoxP3 mRNA expression." (PMID 31141308, 2019). "FOXP3 controls the differentiation and activity of T regulatory cells and may, therefore, have a role in diseases such as asthma." (PMID 31481107, 2019). "Another similar study showed that AS-IV also could attenuate allergic inflammation by regulation Th1/Th2 cytokine and enhancement CD4+CD25+Foxp3+ T cells in ovalbumin-induced asthma." (PMID 30909474, 2019). "Taken together, these findings indicated that anti-inflammatory effect of resveratrol in ovalbumin induced asthma may be mediated by downregulation of miR-34a which in turn upregulated FOXP3." (PMID 30619345, 2018).
asthma (continued). "We believe the data from this study warrant further investigations in severe asthma as to whether the differential effects of oral prednisolone on mDCs, as well as Foxp3+ Tregs, have a translational impact as a biomarker of clinical responsiveness to steroids." (PMID 29130617, 2018). "In conclusion, elevated serum levels of IL-4 and increased expression of GATA3 and GATA3/FOXP3 ratio in PBMCs isolated from patients with asthma indicate an imbalance in the levels of Th2/Treg-related transcription factors and a Th2-deviated pattern in patients with asthma." (PMID 30116273, 2018). "Foxp3 plays a key role in maintaining tolerance to common antigens in asthma and allergy." (PMID 29317916, 2018). "Since GATA3 and FOXP3 are the principal transcription factors of Th2 and Treg cells, respectively, GATA3/FOXP3 mRNA expression ratio may be considered as a useful substitute parameter to determine Th2/Treg cells status in patients with asthma." (PMID 30116273, 2018). "However, the current study results demonstrated that GTAT3/FOXP3 expression ratio in patients with moderate asthma was significantly higher than that of the subjects with severe asthma." (PMID 30116273, 2018). "Furthermore, cell suspensions from the lung were stained with antibodies specific for CD4 and the master transcription factors for T-bet, Gata-3, RORγt, and Foxp3 to better understand the roles of CD4+ T subsets in the pathogenesis of asthma." (PMID 29162668, 2017). "Huai Qi Huang could also regulate Th1/Th2 and Treg/Th17 via the re-balance of cytokine profiles and ratios of transcription factors, T-bet/Gata-3 and Foxp3/RORγt in OVA-induced asthma model mice." (PMID 29162668, 2017). "However, in mouse models of asthma, IL-33 signaling to IL-33R+Foxp3+ Treg cells results in their expression of Th2 cytokines, and abrogation of suppressive ability." (PMID 29045903, 2017). "Therefore, Huai Qi Huang increased the ratio of not only T-bet/Gata-3 but also Foxp3/RORγt, regulating the balance of Th1/Th2 and Treg/Th17 in asthma." (PMID 29162668, 2017). "To examine whether the effects of Foxp3 expression on OVA-induced asthma were mediated by Treg cells, we depleted Tregs in this model by treating OVA-exposed Foxp3DTR mice with diphtheria toxin." (PMID 27633092, 2016). "Consistent with data from other researchers, our results have demonstrated that ectopic expression of Foxp3 could have beneficial effects for individuals with asthma." (PMID 27633092, 2016). "In conclusion, we showed that adenovirus-delivered Foxp3 was expressed in lung epithelial cells and exerted protective effects against allergen-induced leukocyte infiltration, release of pro-inflammatory cytokines and goblet cells metaplasia in asthma models." (PMID 27633092, 2016). "The only difference we have observed previously was in the frequency of FoxP3-positive regulatory T cells, where we showed that there was a higher frequency of FoxP3-positive T cells in the peripheral blood of patients with SS asthma compared with that seen in patients with SR asthma." (PMID 25772594, 2015). "A study of monozygotic twins (MZT) pairs that were discordant for asthma found a decrease in FOXP3 protein expression and impaired Treg function in the asthmatic twin, both of which were associated with increased levels of CpG methylation within the FOXP3 locus." (PMID 27965764, 2015). "However, it was demonstrated that FOXP3 expression shows a negative correlation with IgE, eosinophilia and IFN-γ levels and FOXP3+/CD4+ ratio is significantly low in asthma and atopic dermatitis." (PMID 26023323, 2015). "Glucocorticoids have been suggested to amplify the IL-2-dependent expansion of FOXP3+CD4+CD25+ T cells in vivo, increase FOXP3 expression by Tregs in patients affected by asthma, and restore the impaired suppressive function of Tregs in patients with relapsing multiple sclerosis." (PMID 26379673, 2015).
asthma (continued). "In contrast, regulatory T cells (Treg cells, a CD4+CD25+FOXP3+ subset) have inhibitory effects on asthma airway inflammation, inhibiting the proliferation of other T cells; it is believed they are mediated by cytokines such as tumor growth factor beta (TGF-β) and IL-10." (PMID 26565810, 2015). "Besides SLE patients, treatment with glucocorticoids yields increase in Treg cells and FoxP3 levels in patients with asthma, immune thrombocytopenia purpura patients and multiple sclerosis." (PMID 24475019, 2014). "Thus, there is a correlation of increase in IL-17 levels in patients with asthma coupled with a significant decrease in transcription factor FOXP3 Treg level when compared to controls." (PMID 24995020, 2014). "This imbalance may be important for development of airway obstruction in asthma as we found that decreased FEV1 correlated with the decreasing percentage of CD4+Foxp3+TGF-β+ cells and simultaneously with the increasing percentage numbers of CD4+IL-17+ cells." (PMID 25132806, 2014). "The decreased population of Th3 iTreg cells may, therefore, contribute to the presence of airway inflammation and to asthma progression since there is a correlation between the percentage of CD4+Foxp3+TGF-β+ cells and FEV1." (PMID 25132806, 2014). "Also, NGF is an inducible survival growth factor for T cells, depending on the cytokine profile; anti-NGF treatment enhances Foxp3+ regulatory T cells and decreases Th17 cells in a murine model of asthma." (PMID 24223945, 2013). "Moreover, the Cortex Mori Radicis extract was found to enhance CD4+CD25+Foxp3+ regulatory T cells and suppress Th2 cytokines, thereby improving asthma symptoms." (PMID 23843865, 2013). "Tbet showed the largest change in expression in severe asthma followed by Foxp3, Gata3, and Rorγt." (PMID 23781124, 2013). "Finally, since in asthma the Foxp3 expression is specifically associated with CD4+CD25+ T-cells, we investigated the Foxp3 expression in T-cells with this specific phenotype." (PMID 23573194, 2013). "Therefore, we investigated the effects of EA on CD4+CD25+Foxp3+ Treg cells and the relationship between acupuncture mediated antiallergic effects and Treg-cell responses in a murine model of asthma." (PMID 22649477, 2012). "Because we observed differential levels of FOXP3 transcript between MZT pairs discordant for asthma, we next determined whether changes in FOXP3 expression were associated with altered DNA methylation." (PMID 23226205, 2012). "In asthma patients receiving glucocorticoid treatment, FOXP3 mRNA expression increases." (PMID 22778976, 2012). "Children in a community with high levels of ambient air pollution (Fresno, CA) had increased methylation of the FOXP3 locus, a locus important in Treg-cell function and asthma morbidity, compared with children residing in a low-pollution community (Palo Alto, CA)." (PMID 22591701, 2012). "Finally, inhibition of aerobic glycolysis could not only reduce the production of lactate, IL-5, IL-17, and IFN-γ, but also stimulate that of IL-10 and Foxp3 in a mouse model of asthma." (PMID 39040099, 2024). "Furthermore, we have found links between AAPs and DNA methylation of specific CpG sites of IL10 and FoxP3 genes in children with asthma and more recently that AAP exposure was associated with altered methylation of CpG sites for IFNγ, IL4, IL10, and FoxP3 genes." (PMID 35287715, 2022). "Therefore, in addition to Th2 cells, Th17 cells, RORγt, and Foxp3+ Treg cells may be important therapeutic targets in asthma and airway inflammation." (PMID 33806085, 2021). "Saliva FOXP3 methylation was found to be associated with TRAP exposure during the 1st year of life and persistent wheezing and asthma diagnosis at age 7 in the CCAAPS cohort, suggesting that the epigenome may contribute to the impact of early life TRAP exposure on later asthma risk." (PMID 27777592, 2016).